SAA3P (serum amyloid A3, pseudogene )
Synonyms: SAA3
Gene: Long non-coding RNA gene on chromosome 11 (18,112,472 to 18,116,132, reverse strand). Ensembl gene ENSG00000290741.
Diseases named in the same sentence as SAA3P in open-access papers:
SAA3P is named in the same sentence as 2 diseases in open-access papers, as found by Europe PMC text mining. Sharing a sentence is not in itself a finding about the gene and the disease. The quoted sentences say what the papers report.
adenoma (1 paper, 2023). A neoplasm arising from the epithelium. "Six genes (SAA2, SAA1, CRP, SAA3P, PLA2G2A, and APOA4) listed in the heat map also indicated that the expression of PLA2G2A was limited to the adenoma tissue, following the violin plot results." (PMID 38201587, 2023).
colon cancer (1 paper, 2022). "In addition to the downregulation of cytokines, the inflammatory stimulators IL-6 and SAA3P were also downregulated in MTA1-overexpressing CT26 mouse colon cancer cells." (PMID 35350571, 2022).